LAG3 (lymphocyte activating 3)
Diseases named in the same sentence as LAG3 in open-access papers (continued):
Sharing a sentence is not in itself a finding about the gene and the disease.
tumor (continued). "Concordantly, considering tumor location, in CT of left-sided tumors, low score of LAG3 was associated with no metastasis and no recurrence." (PMID 36765348, 2023). "LAG-3 shows great potential as a target in tumor immunotherapy." (PMID 37575241, 2023). "Previous studies have reported that RNA methylation could influence LAG3's function in tumor immunity." (PMID 38041068, 2023). "In liver metastases, the immunosuppressive checkpoints CTLA-4, LAG-3, B7-H3, and ARG1were highly expressed within the outer invasive margin and distal region, but their levels were lower or similar inside the tumors compared with other metastatic tumor sites." (PMID 37768208, 2023). "Furthermore, other co-inhibitory receptors, such as PD-1, T-cell immunoglobulin and mucin-domain containing-3 (TIM3), and lymphocyte-activation gene 3 (LAG3) are co-expressed on tumor-infiltrating lymphocyte cells." (PMID 36891151, 2023). "While targeting other potential immune checkpoints, small molecules or antibodies that disrupt negative regulation between tumor cells and T cells or between bone marrow cells and T cells, such as LAG3, TIGIT, TIM3, B7H3, CD39, CD73, and Adenosine A2A receptors, are in clinical trials." (PMID 38003338, 2023). "In this study, we aimed to investigate the expression and co-expression status of three immune checkpoints (PD-1, PD-L1, and LAG-3), as well as tumor-infiltrating lymphocytes (TIL) scores, and to further establish their potential correlations with clinicopathologic features." (PMID 37264298, 2023). "Besides, LAG3 knockout-CART cells exhibit vigorous anti-tumor ability in vitro and in a mouse model." (PMID 37569693, 2023). "Additionally, further immunostaining on human tumor tissues confirmed that more CD8+LAG3+ exhausted T cells were detected in Iso1PosIso2Pos niches than Iso1PosIso2Neg niches." (PMID 37047287, 2023). "The ligands of LAG-3 in the tumor microenvironment are MHC II, Galectin-3, and LSECtin." (PMID 37509517, 2023). "An exploratory biomarker analysis included a four-gene gene expression signature (CD8A, STAT1, LAG3, and CD27), TMB (tumor mutation burden), and the pulmonary immune prognostic index (LIPI) measured according to LDH levels and neutrophil/lymphocyte ratios (NLR) in peripheral blood." (PMID 38136333, 2023). "In addition, the TIM was characterized in terms of the type of tumor‐infiltrating cells, the tumor mutational burden (TMB) together with CLTA4/LAG3/ PD‐L1/HAVCR2/ PD‐1 expression profiles." (PMID 37178411, 2023). "Similarly, CRISPR/Cas9 mediated the deletion of lymphocyte activation gene-3 (LAG-3) (a negative regulator of T-cell activity) was found to improve the anti-tumor effect of CAR-T cells in the murine xenograft model." (PMID 38201467, 2023). "Seven ICIs, excluded LAG3 and TIGIT were detected to have higher expression levels in the high-risk group, which may be related to the higher tumor grade of patients in which group." (PMID 37355624, 2023). "In this work, we examined the relationship between immune cells and tumor immune infiltration, and we found that immune inhibitory receptors such as PDCD1, CTLA4, TIM3, and LAG3 may be important for T cell activation in tumor cells." (PMID 38248311, 2023). "Therefore we decided to assess LAG3 expression in 3 additional tumor specimens (one HNSCC, one Hodgkin and one NSCLC)." (PMID 38057799, 2023). "Inhibitory receptors, such as programmed cell death 1 (PD-1), lymphocyte activation gene-3 (LAG-3), T-cell immunoglobulin-3 (TIM-3), and cytotoxic T-lymphocyte-associated protein 4 (CTLA-4), are highly expressed in tumor-infiltrated CD8+ T cells, which results in CD8+ T-cell exhaustion." (PMID 36945005, 2023).
tumor (continued). "LAG-3 expression levels and LAG-3+ cell infiltration in cancer is associated with tumor progression, poor prognosis, and unfavorable clinical outcomes in several human tumor types." (PMID 38162657, 2023). "Notably, we previously reported that RMC tissues upregulated expression of immune-checkpoint receptors such as PD-1, CTLA-4, and LAG3, although PD-L1 expression in tumor cells was notably heterogeneous." (PMID 37568622, 2023). "Furthermore, a pan-cancer bioinformatic analysis was performed to investigate the correlation between LAG3 expression and the tumor immune microenvironment." (PMID 38041068, 2023). "LAG-3 can negatively regulate the function of T cells, exerting important effects on maintaining the homeostasis of the immune system under normal physiological conditions and promoting tumor cell immune escape in the TME." (PMID 37670328, 2023). "Notably, except for LAG-3, a positive correlation was found between the expression of all IRs in the periphery and the tumor site." (PMID 37898752, 2023). "For instance, oncolytic VACVs encoding a single chain variable fragment against TIGIT induced effective anti-tumor immunity and achieved a profound remodeling of the inhibitory tumor microenvironment from a “cold” state to a “hot” state synergizing with PD-1 or LAG-3 blockade." (PMID 38283361, 2023). "In addition, the positive expression of LAG-3 in tumor TIIs was a prognostic factor for disease recurrence and poorer DFS in patients with GTN." (PMID 36875956, 2023). "Antibodies against LAG3 restore immune response of HCC-derived T cells to tumor-specific antigens." (PMID 36845131, 2023). "In addition, novel ICs TIM-3 and LAG-3 are also highlighted as potential therapeutic targets to combine with PD-1 or CTLA-4 ICBs under acidic conditions to boost anti-tumour immunity." (PMID 35708739, 2023). "Notably, the emerging animal experiments and clinical trials have demonstrated that blockade of LAG3 enhances the anti-tumor efficacy, underscoring its potential in cancer therapy." (PMID 38115039, 2023). "AGK2 and aspirin were equally effective with LAG-3 inhibition at suppressing tumor growth." (PMID 37115694, 2023). "Blocking LAG3 can boost the anti-tumor effects of CD8+ T cells in an antigen-specific manner." (PMID 37762493, 2023). "In addition to the expression of PD-L1 or LAG-3, changes in the immunoregulatory genes and the transcriptomic profile of the tumor will reveal which patients can benefit more from immunotherapy." (PMID 36945923, 2023). "Subgroup analysis based on tumor type showed that higher expression of LAG3 was correlated with worse OS in patients with CESC (HR = 1.76, 95% CI 1.03–3.00, P = 0.038), LIHC (HR = 1.76, 95% CI 1.08–2.87, P = 0.024), and SKCM (HR = 1.92, 95% CI 1.15–3.22, P = 0.013)." (PMID 38041068, 2023). "Furthermore, the high levels of PD-1, PD-L1, CTLA-4, LAG-3, SIGLEC15, and TIGIT were associated with poor prognosis and immunosuppression of the tumor microenvironment in ccRCC." (PMID 37175461, 2023). "Several studies have found that ICIs (including PD-1/PD-L1/CTLA4/LAG3) have an important function in maintaining tumor antigen tolerance but are usually hijacked by tumors to mediate their immune escape, leading to poor therapeutic outcomes in some patients with ICI therapy." (PMID 37047824, 2023). "In addition to using mAbs to block ICPs expression and restore tumor-infiltrating immune cell function, several approaches for targeting LAG-3, TIM-3, and TIGIT via immunotherapy, such as the development of BsAbs, have been reported." (PMID 37670328, 2023). "Interestingly, when comparing bladder tissue and tumor samples, increased levels of LAG3 were seen in CD4+ lymphocytes, CD8 and CD127 in CD8+ lymphocytes, as well as SIRP within the monocyte population was found in the bladder." (PMID 36900156, 2023).
tumor (continued). "To characterize the activation of cytotoxic CD4+ and CD8+ T cells, the main cellular mediators of the anti-tumor immunity, we first assayed the expression of the immune checkpoints PD-1, LAG-3, and TIM-3, known to reflect the immune status of TILs in solid tumors." (PMID 36854895, 2023). "Anti-PD-L1 plus anti-CTLA-4 may also be a better option in patients with high lactate dehydrogenase, brain metastases, or mucosal melanoma, while anti-PD-1 plus anti-LAG-3 may be preferred in the elderly and perhaps patients with low tumour burden." (PMID 37507765, 2023). "Importantly, these CD8+ T cells displayed a more prominent activation state but less exhausted phenotype by decreased expression of KLRG1 and LAG3, presumably induced by a greater recognition of TAAs in the tumor niche." (PMID 38235131, 2023). "In addition, we examined the expression levels of PD1, PDL1, CTLA4, TGFB1, TIGIT, IDO1, and LAG3 in 51 tumor samples." (PMID 37928532, 2023). "In line with this hypothesis, Tox-deficient CD8 T cells exhibited reduced cytokine production, killing capacity and tumor persistence despite having diminished expression of inhibitory surface molecules (PD-1, LAG3)." (PMID 38054003, 2023). "To evaluate whether LAG3 mRNA correlates with tumors, we compared LAG3 mRNA expression between normal and tumor tissues from multiple cancers in TCGA." (PMID 38062416, 2023). "Furthermore, multiple immune algorithms have highlighted the important regulatory role of LAG3 for the tumor-infiltrating immune cells including CD8 + T cells, B cells, dendritic cells (DCs), macrophages, and natural killer (NK) cells." (PMID 38115039, 2023). "LAG-3 also has a soluble form (sLAG-3) that provides greater immune control and regulation in the stroma or tumor microenvironment.it has been suggested that sLAG-3 alters the monocytes differentiation into macrophages or DCs, producing APCs with low immunostimulatory capacity." (PMID 38162657, 2023). "In mice, treatment with anti-LAG-3 and anti-PD-1 antibodies also showed a strong anti-tumor effect." (PMID 37727377, 2023). "Since the expression pattern in different pathological types was not significant, these results suggest that the expression of LAG-3 in tumor TIIs may be a prognostic factor and therapeutic target in GTN." (PMID 36875956, 2023). "Furthermore we assessed the presence of immune checkpoint biomarkers (IDO1, ICOS, LAG3 and PD-L1) on tumour epithelial and inflammatory cells across the sample tissues." (PMID 37527282, 2023). "This study also demonstrated that tissue-resident CD8+ T cells (expressing CD69, ZNF683, CD103, PCD1 and LAG3) may promote anti-tumor immunity and appear to expand after ICI administration." (PMID 37173966, 2023). "Furthermore, it is reported that the expressions of CTLA4, PD‐1, LAG‐3, and PD‐L1 were correlated with immunosuppression of the tumor microenvironment." (PMID 37277111, 2023). "Furthermore, continuous antigen stimulation leads to the up-regulation of co-inhibitory signalling molecules such as CTLA-4, PD-1, and LAG-3 on tumour-specific lymphocytes, rendering T cells unresponsive." (PMID 37426674, 2023). "Moreover, the blockade of several immune checkpoints, such as PD-1, CTLA-4, and LAG-3, represents an alternative way of inducing anti-tumor immunity." (PMID 37064017, 2023). "Furthermore, scRNA-seq analysis revealed that CD47 was substantially expressed in tumor cells, and we discovered that riskscore were positively linked with CD47, PDCD1, TIGIT, and LAG3." (PMID 37021054, 2023). "Considering that LAG3 is an inhibitory immune checkpoint that elicits suppressive immune responses and facilitates tumor escape, such a correlation between the expression of this marker and improved survival may be paradoxical." (PMID 36765348, 2023).
tumor (continued). "Blocking of inhibitory checkpoints such as cytotoxic T-lymphocyte-associated protein 4 (CTLA-4), programmed cell death protein 1 (PD-1), programmed cell death ligand 1 (PD-L1) or lymphocyte activation gene 3 (LAG-3) can enhance the function of tumor-reactive T cells and induce anti-tumor immunity." (PMID 37760634, 2023). "We have previously shown in a humanized mouse model recapitulating EBV+ PTLD that two immunologic hallmarks associated with tumor progression are the increased expression of activation/exhaustion markers on CD8+ T cells (PD-1, LAG-3, and TIM-3) and accumulation of CD4+ Tregs." (PMID 37033919, 2023). "Hypoxic tissues secrete various chemokines to upregulate the expression of CTLA4 or LAG3 on Treg cells, as well as the PD-L1 ligand of MDSCs, TAMs and tumor cells, thus blocking the entry of antitumor T cells into the tumor core and promoting the recruitment of immunosuppressive cells." (PMID 38115906, 2023). "We noted enrichment of LAG-3+GZMK+CD8+ T cells in pre-MGD013-treated tumours." (PMID 37735150, 2023). "These tumor-infiltrating CAR T cells underwent rapid loss of functional activity, characterized by an upregulation of intrinsic T cell inhibitory enzymes and surface inhibitory receptors (PD1, LAG3, TIM3, and 2B4)." (PMID 38067255, 2023). "The situation with the tumor microenvironment in MPM might result in multiple correlations between LAG3 and the gene markers of TIICs." (PMID 38062416, 2023). "In accordance, anti-LAG-3 therapy could effectively reduce tumour burden in refractory EBV (+) GC patients." (PMID 37735150, 2023). "In addition, VEGF can cause upregulation in the expression levels of the inhibitory receptors, such as TIM-3, CTLA-4, PD-1, and LAG-3 on T cells and on the expression levels of PD-L1 on tumor cells and MDSCs." (PMID 35037899, 2022). "LAG3 signaling negatively regulates T-helper-cell activation, proliferation, and cytokine secretion, and tumor cells may use this signaling pathway to escape the immune surveillance." (PMID 35327439, 2022). "In addition, CD4 fox p3+ regulatory lymphocytes in liver metastasis contained higher frequencies of PD-L1 and LAG3 than in the primary tumor and peritoneal metastasis." (PMID 36013315, 2022). "Along this line, the MHC-II is also a known ligand of the inhibitory co-receptor LAG3, and their interaction provides immunosuppressive signals; its upregulation in tumor-infiltrating lymphocytes involved LAG3 as a key immune checkpoint in the tumor microenvironment." (PMID 36009442, 2022). "The representative drugs include monoclonal antibodies against programmed cell death receptor-1 (PD-1), cytotoxic T-lymphocyte-associated antigen 4 (CTLA-4), and lymphocyte-activation gene 3 (LAG3), which inhibit T cell activity and contribute to immune evasion from the tumor." (PMID 35596181, 2022). "CB213 is poised to enter clinical development and, through intercepting both PD1 and LAG3 resistance mechanisms, may benefit patients with tumours escaping front-line immunological control." (PMID 34969998, 2022). "High relative levels of tumour-targeting effector T cells and the naïve (LAG-3+) helper T population protected patients from metastatic progression, with the proportion of LAG-3+ cells inversely correlating with the serum content of antagonising pro-inflammatory damaged mtDNA." (PMID 34961902, 2022). "In NSCLC, the co-expression of LAG-3 and PD-1 on TILs and PD-L1 in tumor cells is shown." (PMID 36140182, 2022). "Intra-tumor heterogeneity was seen in both primary and metastatic sites, indicating that if LAG3 expression is used for predictive purposes, more than one biopsy may be indicated." (PMID 36313654, 2022). "In addition to the classical immune checkpoint molecules PD-1 and CTLA-4, T cell immunoglobulin mucin receptor 3 (TIM3, or HAVCR2) and LAG-3 are also included in the field of tumor immunotherapy research." (PMID 35601491, 2022).
tumor (continued). "Thus, LAG-3 targeted strategies currently under clinical development for cancer will also be relevant as immunotherapies for the treatment of non-neoplastic diseases." (PMID 35954196, 2022). "Moreover, LAG-3 and PD-1 blockade upregulated effector T-cell activity, thereby inhibiting tumour growth." (PMID 35494015, 2022). "Furthermore, strong negative correlations were found between frequencies of FoxP3−Helios− T cells and CD4+LAG-3+ T cells in TILs in patients with early tumor stages (r = −0.833, p = 0.008 [early]; r = −0.506, p = 0.079 [advanced])." (PMID 36146549, 2022). "Interestingly, the close association of the DTL gene and markers of Treg cells and T cell exhaustion, such as FOXP3, CCR8, STAT5B, PD-1, CTLA4, and LAG3, was found after adjusting the correlation values for tumor purity." (PMID 35392073, 2022). "On the other hand, the binding of LAG-3 to MHC-II contributes to tumor escape from apoptosis." (PMID 36359346, 2022). "It is unknown whether IHC for LAG3 on tumour infiltrating lymphocytes is an effective biomarker for ICI response, but it may reflect immune surveillance and better prognosis in early-stage disease." (PMID 35054292, 2022). "The anti-tumor effect of ICIs targeting LAG-3, TIM-3 or TIGIT in humans is currently under study." (PMID 35541908, 2022). "However, vaccination combined with dual PD-1 and LAG-3 blockade induced the highest anti-tumor effect in a prostate cancer model in which PD-1 blockade alone with vaccination showed less efficacy." (PMID 36015348, 2022). "In this context, co-inhibitory signals may also arise as in the case of tumor cells expressing receptors PD-1, LAG-3, and Tim-3, which when bound to their cognate ligands on T cells, induce T-cell inactivation." (PMID 34918208, 2022). "Similarly, there were trends toward a significant reduction in TIM-3 and LAG-3 expression on the surface of tumour-infiltrating CD4+ T cells post-FLOT and post-CROSS chemoradiotherapy." (PMID 35366537, 2022). "MHC-II and FGL-1, as ligands of LAG-3, are related to LAG-3-mediated tumour immune escape." (PMID 35494015, 2022). "Importantly, the combination of LAG-3 blockade with specific antitumor vaccination resulted in a significant increase in activated CD8+ T cells in the tumor and disruption of the tumor parenchyma." (PMID 36077354, 2022). "LAG-3 also plays immune adjuvant roles and participates in the tumor immune escape." (PMID 35958563, 2022). "In particular, TIM-3 and LAG-3 were upregulated on tumour-infiltrating T cells and may represent novel targets in combination with PD-1 and/or CTLA-4 ICBs." (PMID 35366537, 2022). "Besides demonstrating the potential for improved anti-tumor activity of specific T cells through genetic editing of LAG-3, PD-1, and TIM-3, we also monitored the systemic toxicity induced by ATT with genetically edited T cells as compared to control T cells." (PMID 35328630, 2022). "LAG-3 acts similarly to PD-1 and helps tumor cells to undergo immune escape." (PMID 35911673, 2022). "The synergy between LAG-3 and PD-1 was demonstrated to fortify tumor-induced tolerance." (PMID 35669786, 2022). "Interestingly, the DEN/CCl4-treated WT mice showed a significant enhanced expression of Lag3 in the surrounding tissue in comparison to tumor tissue." (PMID 35897689, 2022). "In fact, the evaluations of LAG-3 as a biomarker have been confirmed in several tumor types." (PMID 35669786, 2022). "LAG-3 modulates the tumor microenvironment by immunosuppressive effect." (PMID 36077354, 2022). "In addition, multi-targeted ICI combination therapy targeting LAG-3 can improve anti-tumor efficacy because LAG-3 is frequently co-expressed with PD-1 on TILs." (PMID 36225938, 2022). "Using the MC38 tumor model, we first investigated the LAG3 expression on TILs." (PMID 36180876, 2022). "Furthermore, [89Zr]Zr-DFO-REGN3767, a fully human anti-LAG-3 mAb, was shown to detect LAG-3 expression in mouse tumours." (PMID 36297474, 2022).